PYGL (glycogen phosphorylase L)
Diseases named in the same sentence as PYGL in open-access papers (continued):
Sharing a sentence is not in itself a finding about the gene and the disease.
esophageal cancer (3 papers, 2021 to 2025). A primary or metastatic malignant neoplasm involving the esophagus. "KCNMB2-AS1 is highly expressed in esophageal cancer tissues and directly interacts with miR-3194-3p, potentially by upregulating glycogen phosphorylase L." (PMID 40191723, 2025). "KCNMB2-AS1 promotes esophageal cancer development by binding to miR-3194-3p and further upregulating PYGL expression." (PMID 35899200, 2022).
glioblastoma (3 papers, 2021 to 2023). The most malignant astrocytic tumor (WHO grade IV). "Similarly, it has been shown previously that knockdown of glycogen phosphorylase liver isoform (PYGL) sensitizes glioblastoma cells to radiation treatment." (PMID 37816729, 2023). "However, experimental data of bevacizumab treatment suggest that, unlike PYGL, neither PYGM or PYGB exhibited a detectable increase in U87 (glioblastoma) cells." (PMID 34177761, 2021).
McArdle disease (3 papers, 2013 to 2023). "In genes related to glycogen catabolism, PYGB, PYGL, and PYGM, only PYGM is expressed in the muscle, and when carrying biallelic mutations it causes McArdle disease (glycogen storage disease type V)." (PMID 37185710, 2023).
Sepsis (3 papers, 2021 to 2025). Sepsis is defined as life-threatening organ dysfunction caused by a dysregulated host response to infection. "The protein expression levels of four upregulated necroptosis‐related DEGs (PYGL, TNF‐α, CYLD and FADD) were significantly higher in the sepsis group than in the control group in all three cells, whereas the TLR3 level was only significantly higher in HUVEC cells." (PMID 40318009, 2025). "Regarding the prediction of mortality in patients with sepsis, the levels of corresponding proteins to the three upregulated necroptosis‐related genes showed excellent or considerable accuracy (AUC; TNF‐α = 0.904, PYGL = 0.851 and CYLD = 0.846)." (PMID 40318009, 2025). "In addition, metabolism-related genes, including PFKFB3, PRKAA1, PYGL, and GYG1, were also upregulated, which indicated their potential roles in mediating immune responses in sepsis." (PMID 34907156, 2021).
acute lymphoblastic leukemia (2 papers, 2015 to 2021). Leukemia with an acute onset, characterized by the presence of lymphoblasts in the bone marrow and the peripheral blood. "PYGL was found to be highly associated with disease recurrence in a study of childhood acute lymphoblastic leukemia." (PMID 33912561, 2021). "PYGL is a liver-type of glycogen phosphorylase and mutation of its gene is associated with high risk of relapse of childhood acute lymphoblastic leukemia." (PMID 25577646, 2015).
colorectal cancer (2 papers, 2020 to 2025). A primary or metastatic malignant neoplasm that affects the colon or rectum. "PYGL, which was previously associated with colorectal cancer risk, showed a correlation of 0.51 between measured and predicted gene expression based on data from GTEx." (PMID 33142733, 2020). "Subsequently, computer-aided drug design was utilized to screen multiple compounds exhibiting low binding energy with the PYGL protein, providing new therapeutic targets and directions for colorectal cancer treatment." (PMID 41144378, 2025).
depression (2 papers, 2021 to 2024). "In glycogenolysis, PYGM was downregulated in major depressive disorder and upregulated in ketosis, whereas PYGL was upregulated in both." (PMID 39125835, 2024).
hepatocellular carcinoma (2 papers, 2021 to 2022). A malignant tumor that arises from hepatocytes. "Inhibition of PYGL induced cell death in hepatocellular carcinoma cell and potentiated the effects of multikinase inhibitors." (PMID 35764612, 2022).
Hyperglycemia (2 papers, 2022 to 2026). An increased concentration of glucose in the blood. "Future studies should evaluate the role of PYGL in people with T1D and hyperglycemia." (PMID 41560719, 2026). "The PYGL gene encodes liver glycogen phosphorylase, the rate-limiting enzyme in glycogenolysis, and our patient's variant was consistent with GSDVI carrier status, which may predispose to hepatic glycogenosis during periods of hyperglycemia." (PMID 41560719, 2026).
lung adenocarcinoma (2 papers, 2023 to 2025). A carcinoma that arises from the lung and is characterized by the presence of malignant glandular epithelial cells. "Other studies have shown that high expression of PYGL is associated with poor prognosis in patients with lung adenocarcinoma." (PMID 40735606, 2025).
ovarian carcinoma (2 papers, 2022 to 2023). A malignant neoplasm originating from the surface ovarian epithelium. "In another study, it was found that PYGL was up-regulated in cisplatin-resistant human ovarian carcinoma cell line SKOV3/DDP when compared to cisplatin-sensitive human ovarian carcinoma cell line SKOV3." (PMID 36338962, 2022). "The proteomic analysis exhibited the expression of PYGL, the liver isoform of glycogen phosphorylase, in SKOV3ip1 and TYK-nu ovarian cancer cell lines." (PMID 36338962, 2022).
cervical cancer (1 paper, 2024). A primary or metastatic malignant neoplasm involving the cervix. "We employed the cervical cancer cell lines HCC94 and CaSki by manipulating the expression of key enzymes PCK1, PYGL, and GYS1, which are involved in glycogen metabolism, through siRNA transfection." (PMID 38871968, 2024).
COVID-19 (1 paper, 2024). A disease caused by infection with severe acute respiratory syndrome coronavirus 2. "The role of the remaining eight key genes (ALDH1L, EME1, PYGL, NNMT, PHGDH, CD52, CD3D, and ESM1) in COVID-19 and sarcopenia has been less studied, emphasizing their importance in future research." (PMID 38978778, 2024).
human papillomavirus infection (1 paper, 2023). "Similarly, the PYGL high expression group was highly associated with PI3K signaling, the Hippo pathway, human papillomavirus infection, extracellular matrix organization/assembly, and epidermis development." (PMID 37371537, 2023).
Hyperinsulinemia (1 paper, 2020). An increased concentration of insulin in the blood. "In agreement with the hyperinsulinemia but the hypoglucagonemia found in U newborns, the physiological induction of PYGL and PEPCK was virtually absent in restricted animals." (PMID 33077861, 2020).
iron deficiency (1 paper, 2020). "The proteome profile identified 4 novel factors to be conversely regulated upon iron deficiency versus iron excess, namely CPT1A, MMP14, XDH, and PYGL." (PMID 33023155, 2020).
lung carcinoma (1 paper, 2025). "Low expression of PYGL can significantly inhibit the proliferation and migration of lung cancer cells." (PMID 40735606, 2025). "Some scholars found that the expression level of glycogen phosphorylase L (PYGL) in lung cancer tissue is significantly higher than that in normal lung tissue, and the expression level of PYGL is positively correlated with the poor prognosis of lung cancer patients." (PMID 40735606, 2025).
lymph node metastasis (1 paper, 2023). "Correlation analysis was performed to investigate the relationship between expression levels of PYGL and HPRT1, tumor size, and lymph node metastasis." (PMID 37371537, 2023).
malignant glioma (1 paper, 2025). A grade III or grade IV glioma arising from the central nervous system. "Previous studies have demonstrated that the acute knockdown of PYGL and the subsequent glycogen accumulation in malignant gliomas constricted the flux into PPP which provoked excessive ROS accumulation." (PMID 40263302, 2025).
melanoma (1 paper, 2019). A malignant, usually aggressive tumor composed of atypical, neoplastic melanocytes. "With regard to the genes specifically up-regulated in the MCSP CTC fraction, the majority have been involved in metastasis (LOXL4, ST6GALNAC2, PYGL), tumour growth (PLK2, CYSTM1, GLUL), and/or melanoma biology (SEC31A, WIPI1, SKP1)." (PMID 30769764, 2019).
Niemann-Pick disease, type C1 (1 paper, 2025). Type C Niemann-Pick disease associated with a mutation in the gene NPC1, encoding Niemann-Pick C1 protein. "This was followed by PYGL gene (GSD6, 6 patients/7 variants), NPC1 (Niemann-Pick disease type C1, 5 patients/6 variants) and SLC37A4 (GSD1b/1c, 5 patients/4 variants)." (PMID 41165782, 2025).
pancreatic ductal adenocarcinoma (1 paper, 2021). An infiltrating adenocarcinoma that arises from the epithelial cells of the pancreas. "Recently, a weighted gene co-expression network analysis (WGCNA) study suggests that PYGL protein can be used as the prognostic biomarker for the survival of pancreatic ductal adenocarcinoma." (PMID 34177761, 2021).
prostate carcinoma (1 paper, 2021). A carcinoma that arises from epithelial cells of the prostate gland. "Additionally, PYGL was identified as a metastasis-associated metabolic gene in prostate cancer." (PMID 34257566, 2021).
psoriasis (1 paper, 2023). An autoimmune condition characterized by red, well-delineated plaques with silvery scales that are usually on the extensor surfaces and scalp. "According to previous reports, glycogen phosphorylase (PYGL) and complement component 5a receptor (C5aR1) promote the inflammatory response in psoriasis." (PMID 37226132, 2023).
tumor (32 papers, 2014 to 2026). "The risk score of all tumor samples was counted as follows: Risk score = (0.974* B4GALT3) + (0.418* PYGL) + (0.195* GALNT14) + (−0.413* FUT2) + (−0.886* GALNT16)." (PMID 38244579, 2024). "We demonstrated that tumor-associated macrophages (TAMs) in GBM tissues expressed a high level of PYGL." (PMID 34177761, 2021). "However, while decreased expression of PYGL in the tumor may result in tumor senescence, our results suggest that decreased PYGL expression is associated with increased risk of CRC." (PMID 30820706, 2019). "PYGL represents a key oncogenic driver and potential therapeutic target linking cellular metabolism to tumor progression and immune evasion." (PMID 42027581, 2026). "CASP8 and PGAM5 were identified as potential biomarkers among these, while previous studies have shown that ZBP1, TLR3, and PYGL contribute to tumor progression in KIRC." (PMID 40969770, 2025). "Integration of GWAS and RNA-seq revealed that 24 CRC-associated genes, including PYGL, SMAD7, and TCF7L2, are involved in tumor metabolism and Wnt/TCF signaling." (PMID 41144378, 2025). "Then, immunohistochemistry (IHC) staining of tissue microarray was performed and confirmed that high PYGL protein expression was detected in 55/90 of pancreatic tissues, but only in 22/90 of the adjacent non-tumor tissues." (PMID 37063425, 2023). "The expression level of PYGL was found to be positively correlated with tumor size (p < 0.05) and lymph node metastasis (p < 0.05)." (PMID 37371537, 2023). "Calculating the expression of four genes, PYGL was highly expressed in METArisk-high and tumor groups, while the others were highly expressed in METArisk-low and normal groups." (PMID 37420300, 2023). "PYGL was finally selected as the key biomarker of our research, for it can lead to poorer prognosis, and was highly expressed both in tumor and METArisk-high group in transcriptional level, and also in HNSCC samples in translational level." (PMID 37420300, 2023). "Drug resistance analysis and xenograft tumor model supported that PYGL enhanced the resistance of HNSCC to cisplatin, leading to its progression and metastasis." (PMID 37420300, 2023). "We for the first time showed increased PYGL protein expression in PDAC tissues, which was positively associated with tumor size, vascular invasion, and TNM stages." (PMID 37063425, 2023). "Established by subcutaneously injecting HNSCC cell lines with PYGL knocked down into female BALB/c nude mice, xenograft tumor model was applied to validate the function of PYGL to cisplatin resistance of HNSCC." (PMID 37420300, 2023). "In order to verify the in vitro results from Tranwell migration and invasion assays, we investigated the effects of PYGL on tumor metastasis in vivo using liver metastasis model via intrasplenic injection." (PMID 37063425, 2023). "Given the role of ROS in AHR regulating PYGL, we pretreated tumor-bearing mice with antioxidants including NAC or GEE before drug treatment." (PMID 38099490, 2023). "Patients overexpressing ANXA5, FKBP10, MSN, and PYGL in the tumor tissues had significantly shorter OS compared to the low expressed group in IS1–IS3 subtypes." (PMID 34512630, 2021). "Favaro and his colleagues found that the depletion of PYGL would trigger glycogen accumulation, induce premature senescence of cancer cells and strongly inhibit tumor growth." (PMID 31754332, 2019). "These in vivo data suggested that resibufogenin inhibits tumor growth through inducing RIP3-mediated activation of PYGL, GLUD1 and GLUL to induce necroptosis in CRC cells." (PMID 30029665, 2018). "Inhibition of PYGL activity was demonstrated to have striking effects on tumor cell viability, inducing senescence, and markedly impairing experimental tumor growth." (PMID 24491179, 2014). "The heat map shows that genes such as CHEK1, PIK3CD, and PYGL are upregulated in tumor tissues." (PMID 40699827, 2025).
tumor (continued). "Previous studies have found that PYGL levels increased more slowly in hypoxia, and reached maximal levels at 72 h, and analysis of PYGL expression in tumor cells revealed distinct patterns of induction by hypoxia (0.1% O2) that were consistent at both the mRNA and protein level." (PMID 34177761, 2021). "We detected these three glycogen phosphorylases in CCRCC and CHRCC to clarify the different mechanisms underlying glycogenolysis in the two tumor types Western blotting confirmed that PYGL was mainly upregulated in CCRCC and PYGL downregulation and PYGB upregulation were the features of CHRCC." (PMID 32127786, 2020). "In contrast with this report, we documented that PYGL expression was induced by hypoxia a HIF1α-dependent manner as evidenced by siRNAs targeting HIF1α and luciferase reporter assay, which may due to the different tumor context." (PMID 37063425, 2023). "Furthermore, the findings suggested that HPRT1 and PYGL might play critical roles in reshaping the tumor microenvironment." (PMID 37371537, 2023). "Thus, ANXA5, FKBP10, MSN, and PYGL might be presented by APCs to the T cells and recognized by the B cells to induce a tumor response." (PMID 34512630, 2021). "Therefore, we can presume that PYGL was likely to be involved in the main glycogen phosphorylase (GP) activity required for glycogen breakdown in hypoxic cells, and helps to promote further cell proliferation in the tumor." (PMID 34177761, 2021). "Second, whether KCNMB2-AS1 promotes tumor growth in vivo by targeting PYGL remains to be explored." (PMID 34516362, 2021). "Therefore, we can hypothesize that PYGL involves in the crosstalk of these signaling molecules and cellular events during tumor growth, metastasis, and angiogenesis." (PMID 34177761, 2021). "PYGL is responsible for breaking down glycogen into the glycolytic pathway, or the PPP, which is of great significance in the radioprotection of tumor cells." (PMID 40263302, 2025). "Our findings revealed that in drug-resistant tumor stem cells, the enzyme PCK1 enhances the phosphorylation of PYGL, leading to increased glycogen breakdown." (PMID 38871968, 2024). "A preclinical study showed that PYGL induces EMT and metastasis in PC by stimulating the glycolysis of glycogen accumulated in tumor cells." (PMID 37628967, 2023). "We identify PYGL, ASPH and CD45 as spatial markers for tumour boundary and reveal immune response-driven, spatially-organised protein networks of the extracellular tumour matrix." (PMID 38001067, 2023). "To assess the roles of PYGL and HLA-B in CRC, we further examined the expression of these two genes sequenced from normal and tumor samples." (PMID 35204406, 2022). "Immunostaining of histological sections also showed that resibufogenin stimulated the expression of RIP3, PYGL, GLUD1 and GLUL in the tumor tissues." (PMID 30029665, 2018). "Moreover, we found that AHR inhibition or knockout led to decreases in p-PYGL and NADPH/NADP+ ratios and increased ROS levels in the DRCs, as well as smaller tumor sizes and prolonged survival of the mice." (PMID 38099490, 2023). "Their expression is consistent with the large field-of-view data, with PYGL and PRPH showing opposite expression patterns across the margin between solid tumour (high PYGL, low PRPH) and brain/tumour interface (low PYGL, high PRPH) and haemoglobin co-localising with the visible blood vessels." (PMID 38001067, 2023). "The expression of GYS1 is HIF1α-dependent, but PYGL is not consistently HIF1α-dependent; PYGL depletion impairs tumor growth, as glycogen breakdown is integral to tumor cell function and growth." (PMID 38028629, 2023).
tumor (continued). "The glycogen degradation by PYGL was shunted to the pentose phosphate pathway which generated ribose 5-phosphate and nicotinamide adenine dinucleotide phosphate (NADPH), which was essential in protecting cells from reactive oxygen species (ROS) and strongly supported tumor growth." (PMID 35281731, 2022).